STAT3 (signal transducer and activator of transcription 3)
Diseases named in the same sentence as STAT3 in open-access papers (continued):
Sharing a sentence is not in itself a finding about the gene and the disease.
cancer (continued). "A dihydroimidazolone derivative, napabukasin (BBI-608), has been tested in clinical trials to reduce the activity of STAT3-dependent genes in cancer cells; however, its mechanism is not entirely clear, and it is believed to act as a proxy killer of STAT3-activated cells." (PMID 40650173, 2025). "Our findings showed that ICM treatment inhibited the phosphorylation of constitutively activated STAT3, suggesting that targeting the nucleo-cytoplasmic translocation of HMGB1 may offer a potential therapeutic strategy against cancers with constitutive STAT3 activation." (PMID 40389855, 2025). "Therefore, the effect of 1 might not be dependent on AR, 1 might suppress proliferation and metastasis in PCa by disrupting other key cancer signaling pathways like mTOR/AKT and STAT3." (PMID 40374533, 2025). "Our study unveils EGFR‐STAT3 as an axis of oncogenic signaling driven by overexpression of the ETS transcription factor ETV1 and provides supporting evidence for the therapeutic potential of combining EGFR and STAT3 inhibitors in targeting (prostate) carcinomas with ETV1 overexpression." (PMID 40808640, 2025). "Thus, the mechanism of constitutive STAT3 activation may be important for CSC development, dedifferentiation of differentiated cancer cells into CSCs, and CSC maintenance." (PMID 38760429, 2024). "Because IL-6 is an upstream target of STAT3 and elevated IL-6 levels in cancer patients have prognostic significance regardless of the cancer type, several compounds targeting IL-6 or IL-6R have been developed and are used for both non-malignant and malignant diseases." (PMID 38339245, 2024). "It was shown that wild-type BLCAP could inhibit the phosphorylation of signal transducer and activator of transcription 3 (STAT3) by directly interacting with it, whereas over-edited BLCAP lost its ability to inhibit STAT3 activation, which in turn promoted cancer progression." (PMID 38233935, 2024). "Hence, in this study, the anti‐cachexia effects of BSN were deciphered and it was observed that BSN could attenuate cancer cachexia‐induced muscle and adipose tissue atrophy through diverse molecular mechanisms including inhibition of COX‐2 and STAT3." (PMID 38807976, 2024). "miR-15b exerts its effects in these cancers through various mechanisms, such as the regulation of proliferation, apoptosis, epithelial–mesenchymal transition (EMT), and drug resistance, mediated by the NF-κB, STAT3, AKT/mTORC1, CDC42/PAK1, and β-catenin signalling pathways." (PMID 39456841, 2024). "In other cancers, the anticancer mechanism of parthenolide is believed to be mainly related to the inhibition of NF-κB, and other mechanisms include the inhibition of mouse double minute 2 homolog (MDM2), HDAC1, transcription protein 3 (STAT3), and glutathione (GSH)." (PMID 39595109, 2024). "EGFRV948R transfection retained STAT3 phosphorylation in EGFR−/−, TMEM25−/− TNBC cells, strongly suggesting that EGFR can phosphorylate STAT3 in the monomeric form in the absence of TMEM25 and thereby relays sustainable proliferative signals to cancer cells to provide the growth advantage." (PMID 38532948, 2024). "Thus, the activation of STAT3 by the PRMT5/MEP50/STAT3 complex discovered in this study may be a new and specific target for suppressing STAT3 for cancer therapeutic approaches." (PMID 38760429, 2024). "Overall, STAT3 inhibition reversed the unfavorable effects of LDHC silencing in HCC-1954 cells and reduced the cancer cell survival of siCTRL cells, indicating that HCC-1954 cells do not benefit from LDHC-targeted therapy but may benefit from monotherapy with STAT3 inhibitors." (PMID 39001513, 2024). "Next, to investigate whether IL6-dependent STAT3 activation is essential for CALB2 expression in cancer cells, various concentrations of stattic (MCE, #HY-13818), a potent STAT3 inhibitor, were added to the cancer cells with rhIL6 treatment." (PMID 39358777, 2024).
cancer (continued). "Moreover, specific DCN knockdown in breast fibroblasts modulated the expression/secretion of several CAF biomarkers and cancer-promoting proteins (α-SMA, FAP- α, SDF-1 and IL-6) and enhanced the invasion/proliferation abilities of these cells through activation of the STAT3/AUF1 signaling." (PMID 38667295, 2024). "We found a significantly higher expression of STAT1 in cancer; however, the counts in non-neoplastic tissue were relatively high, and with 12% of the patients having threefold expression of STAT3 in cancer, the difference between cancer and non-neoplastic tissue was modest." (PMID 38979413, 2024). "STAT3 inactivation is catalysed by PTPRM dephosphorylation and leads to cancer cell death, therefore errors incurred in STAT3 dephosphorylation, such as promoter hypermethylation induced PTPRM transcriptional silencing, may lead to cancer initiation and progression with poor clinical prognosis." (PMID 38475971, 2024). "The mechanisms triggering mitochondrial translocation to engage this non-canonical role of STAT3 have to be further investigated to provide clearer insights on how canonical and non-canonical function can be utilized effectively in immunotherapy cancer therapeutics." (PMID 38538285, 2024). "In addition, adipose tissue also leads to the activation of cancer signaling pathways (phosphoinositide 3-kinases [PI3K], mitogen-activated protein kinase [MAPK], IKK, signal transducer and activator of transcription 3 [STAT3])." (PMID 38768058, 2024). "Although it is well known that STAT3 activation is involved in some features of cancer cells, STAT3 inhibitors have not been used to treat CRCs yet; however, there are inhibitors that have shown encouraging effectiveness in preclinical studies that have entered clinical trials." (PMID 39000238, 2024). "Therefore, although the dependence may vary by cancer type, our data demonstrate that the PRMT5/MEP50/STAT3 pathway is important for CSCs in NSCLC." (PMID 38760429, 2024). "The factors/mechanisms regulating XIAP in CRC remain poorly characterized even though indirect evidence suggests that intracellular pathways (e.g., NF-kB and STAT3), which are highly activated in CRC cells and involved in cancer cell metastasis, could up-regulate XIAP expression." (PMID 39001432, 2024). "In addition, the expression of p-STAT3 and its downstream transcription target VEGF, which are involved in cancer cell growth, angiogenesis, and metastasis, were also decreased in a dose-dependent manner in DU145 cells but did not affect the expression of these proteins in HPrEC cells." (PMID 39590337, 2024). "REVs were found to enhance the expression of CAFs related proteins like αSMA, CD95, EMT marker vimentin, SLC1A5, and STAT3 phosphorylation as well as FAP expression after 48 hours exposure to REVs and SEVs suggesting that REVs can subvert stromal fibroblasts to adopt a cancer-promoting phenotype." (PMID 39431017, 2024). "The relationship between Lin28/NONO/STAT3 could provide promising insights into cancer cell chemoresistance mechanisms." (PMID 38328550, 2024). "Targeting STAT3, in combination with existing anti-neoplastic agents, may prove to be a successful therapeutic strategy to either prevent or even overcome ADR to standard and novel cancer therapies." (PMID 36902166, 2023). "In a cancer context, no data are available in the literature on STAT3 and HPF." (PMID 36674794, 2023). "Therefore, we hypothesized that FGF3 binding to FGFR1, leading to STAT3 phosphorylation, is one of the pathways by which FGF3 exerts its cancer-promoting function." (PMID 37496658, 2023). "SHP1 dephosphorylates the signal transducer and activator of transcription 3 (STAT3), extracellular signal-regulated kinase (ERK), protein kinase B (Akt), and other signaling components, thereby contributing to a decrease in cancer cell proliferation and survival." (PMID 36985458, 2023).
cancer (continued). "It is also known that IL-6 binds to its receptors forms a complex that activates the STAT3; thus, the STAT3 is phosphorylated via the JAK, and this activation is preferred by the PKM2, which leads to the promotion of serine hydroxymethyltransferase 2 transcription in cancer." (PMID 37514090, 2023). "STAT3 is activated in cancer cells as well as in non-cancerous cells." (PMID 37296634, 2023). "Thus, therapeutic approaches that specifically downregulate STAT3 transcriptional activity and/or upregulate STAT1 transcriptional activity may be promising in cancer treatment." (PMID 38022653, 2023). "Indeed STAT3 activation can upregulate the expression of MMP, which, in turn, could favor cancer cell invasion and metastasis." (PMID 36982677, 2023). "Although STAT3 oncogenic properties were classically attributed to Y705 phosphorylation, S727 phosphorylation has also emerged as an event that enhances STAT3 transcriptional activity in addition to non-genomic roles that promote cancer development." (PMID 37945711, 2023). "Furthermore, recent studies indicate that TNF-α and IL-6 promote cancer cachexia in different types of cancer, including gastric and CRC, by protein 16 containing PR domain (PRDM16) gene overexpression via the STAT3 signaling pathway, which induces the browning of WAT." (PMID 37760840, 2023). "Phosphorylation of STAT3 resulted in the activation of the transcription factor NANOG, which is responsible for regulating the properties of the epithelial-mesenchymal transition (EMT), on the one hand, and maintaining the stemness of cancer stem cells (CSCs) on the other." (PMID 36835075, 2023). "In addition, studies have shown that PGAP3, GRB7, STARD3, and PSMD3 are significantly positively correlated with STAT3 in TCGA cancers; however, reports on these are lacking." (PMID 36977736, 2023). "Cancer migration and angiogenesis could also be inhibited by erianin through modulating the expression of ERα, p-ERK1/2, MMP2, MMP9, TIMP1/2, COX-2, HIF-1α, and IL-6, or the activation of JAK2/STAT3." (PMID 36678588, 2023). "Additionally, the distribution of STAT1, STAT2, STAT3, STAT4, STAT5A, STAT5B, and STAT6 expression in CD4+ T cells in pan-cancer were also clearly illustrated, which showed that STAT1 and STAT2 expression were notably up-regulated in CD4+ Treg cell with marker OSA1 and CD4+ T cell with ISG IFIT1." (PMID 36968603, 2023). "Our findings highlighted that PRMT6 overexpression significantly elevated the expression of Vimentin, twist, and N-cadherin, while concurrently downregulating E-cadherin expression in cancer cells expressing STAT3 WT, but not in those expressing STAT3 R729K mutant." (PMID 37813837, 2023). "Experiments conducted on cancer cell lines have demonstrated that the conserved RMLDVEKC motif of the PD-L1 intracytoplasmic tail is related to the inhibition of STAT3 Y705 phosphorylation and the prevention of STAT3 upregulation in the line to avoid IFN cytotoxicity." (PMID 37834467, 2023). "Once detached from ECM, α6β4 integrin on cancer cells inhibited the expression of long polyunsaturated fatty acid-rich enzyme acyl-CoA synthetase long-chain family member 4 (ACSL4) (essential for ferroptosis) through Src and signal transducer and activator of transcription 3 (STAT3) pathways." (PMID 37369681, 2023). "STAT3 is a transcription factor oncogene involved in the IL-6-JAK-STAT3 signaling cascade that mediates gene expression in response to cell stimuli and thus plays a central role in cell growth and apoptosis across multiple cancers, and their targeting has shown therapeutic benefits." (PMID 37746266, 2023). "In addition, crosstalk exists between STAT3 signaling and Snail-Smad3/TGF-β1 in cancers." (PMID 38136312, 2023).
cancer (continued). "EGCG has shown multiple effects on the major signaling pathways governing carcinogenesis and cancer progression, including MAP kinase (MAPK), phosphatidylinositol-3 kinase (PI3K), nuclear factor κB (NFkB), and reducing the increased levels of phosphorylation of ERK1/2 and Jak/STAT3." (PMID 37445915, 2023). "However, the involvement of STAT3 S-palmitoylation in cancer and the regulation of S-palmitoylation has not yet been reported." (PMID 38051779, 2023). "Inhibition of STAT3 may be important because the Janus kinase/signal transducers and activators of transcription (JAK/STAT) pathway plays a key role in membrane-to-nucleus signalling, which is critical in mediation of cancer and inflammation." (PMID 37446864, 2023). "However, because the diverse biology of STAT3 and its activators in cancer is complex, its biological functions in cancer cells are not clear." (PMID 36151091, 2022). "We propose that Stat3 activation downstream of persistent RET signaling unleashes apoptosis, accelerating the involution process, and could simultaneously increase inflammation, culminating in chronic Stat3 activation-promoting cancer." (PMID 35044452, 2022). "This, in turn, can enable combating widespread strategies used by cancer cells to resist the action of drugs, such as MET amplification or PI3K/AKT activation after targeted EGFR inhibition, PI3K/AKT compensation after mTOR inhibition, or MAPK/STAT3 cross-talk." (PMID 35913978, 2022). "Given the reported roles of STAT3 in cancers, in which RNF7 overexpression has also been observed, it will be interesting to examine whether the regulation of SOCS1/JAK/STAT3 by RNF7 also operates in other cancer types." (PMID 35562668, 2022). "Inhibition of STAT3 could prove useful for IBM and LGL, as well as for cancer-induced cachexia." (PMID 35806366, 2022). "Exosomal glycoprotein-130 (gp130) obtained from breast cancer cells was also observed to contribute to the progression of cancer through the activation of the IL-6/STAT3 pathway in macrophages thus leading to the alteration of normal macrophage phenotypes into pro-cancer phenotypes." (PMID 36406206, 2022). "Signal transducer and activator of transcription 3 (STAT3) is both a signaling molecule and a transcription factor, while the mammalian homolog of Kirsten RAS (KRAS) is a signal relaying GTP-binding protein, however, both have been popular yet elusive targets in the world of cancer therapy." (PMID 35886918, 2022). "The Candida albicans (C. albicans)-driven release of IL-7 from macrophages promotes aryl hydrocarbon receptor (AhR) and phospho-STAT3 (p-STAT3) binding at the IL-22 gene in ILC3s, which subsequently triggers the transcription of this cytokine for CAC formation in C. albicans AOM-DSS cancer model." (PMID 36341381, 2022). "However, our results as well as previous studies in other cancers do raise the possibility that upregulation of other signaling pathways, particularly JAK/STAT3 activation, could potentially compensate for MEK inhibition following treatment of both diseases." (PMID 35835937, 2022). "Moreover, Stat3 can activate the transcription of MMP2, MMP9, and Snail in cancer cells." (PMID 35178453, 2022). "Therefore, it is not hard to imagine that Pdia4 can directly interact with Stat3 in the cytosol and nucleus of cancer stromal cells, leading to the up‐regulation of Vegf gene expression." (PMID 35170261, 2022). "CAF‐produced IL6 also could promote cancer metastasis through TGFβ‐induced EMT and STAT3 signal." (PMID 35978854, 2022). "Interestingly, a study by Zimmers and colleagues showed that deletion of STAT3 did not result in skeletal muscle changes in animal models without cancer." (PMID 35328423, 2022).
cancer (continued). "In cancer patients, the probable mechanism of function is based on the stimulation of adenosine monophosphate-activated protein kinase (AMPK) followed by the inhibition of PI3K, mTOR and ERK/STAT3 signaling pathways, the deprivation of energy support for cancer cells and their apoptosis." (PMID 35269636, 2022). "Indeed, the inhibition of STAT3 and SOCS3 has been shown to reverse cancer-related muscle wasting." (PMID 35626644, 2022). "In addition, STAT3 promotes MMP2 and MMP9 and enhances cancer cell invasiveness." (PMID 35799305, 2022). "For cancer initiation and development, TRIMs may play a role through the JAK/STAT3 pathway: knockdown of TRIM66 reduced the activation of phosphorylation levels of JAK2 and STAT3 in CRC cells, and significantly inhibited cell proliferation, migration, and invasion of CRC cells." (PMID 36261847, 2022). "In addition, CRP may mediate carcinogenesis and cancer progression via activation of the FcgRs/MAPK/ERK, FcgRs/NF-κB/NLRP3, and FcgRs/IL-6/AKT/STAT3 pathways." (PMID 35847918, 2022). "IL-37 exerts a negative effect on cancer cell proliferation and invasion through STAT3 signaling." (PMID 36237303, 2022). "Using pharmacological inhibitors to analyze the proliferation, metastasis and invasion of cancer cells and the expression of EMT-related markers, we further showed that MAL inhibited the proliferation, metastasis and invasion of GC cells and interfered with the EMT by inhibiting STAT3." (PMID 35093120, 2022). "Cervical cancer-secreted exosomal miR-1468-5p epigenetically activates the JAK2/STAT3 pathway in lymphatic endothelial cells by directly targeting homeobox containing 1 (HMBOX1) in the SOCS1 promoter, activating an immunosuppressive program that allows cancer cells to escape anti-cancer immunity." (PMID 36358833, 2022). "Moreover, QC-mediated anti-inflammatory and anti-apoptotic properties play a key role in cancer prevention by modulating the TLR-2 (toll-like receptor-2) and JAK-2/STAT-3 pathways and significantly inhibit STAT-3 tyrosine phosphorylation within inflammatory cells." (PMID 36233051, 2022). "Further, to assess whether the cytotoxicity of the EOs is specific to cancer cells, we treated non-transformed human fibroblasts with increasing concentrations of strong anti-STAT3 EOs for 24 h." (PMID 35956786, 2022). "To determine whether WBC100 could affect c‐Myc stability in cancer cells, we examined its effects on c‐Myc and other nuclear proteins including XPB, the largest subunit of RNA polymerase II (Rpb1), and STAT3 in various cancer cells, respectively, using western blotting." (PMID 35048559, 2022). "Similarly, curcumin was also found to inhibit the pathways that are mediated by another transcriptional factor, namely, signal transducer and activator of transcription 3 (STAT3), which is solely responsible for cancer cell survival, angiogenesis and metastasis." (PMID 34959384, 2021). "However, the combination effects of TLR activation and STAT3 inhibition have not been studied in the context of cancer immune therapies." (PMID 34452929, 2021). "Moreover, HDAC1 has previously been implicated in regulating STAT3 nucleocytoplasmic partitioning and activity, wherein HDAC1 expression was shown to reduce nuclear accumulation of STAT3 in commonly used cancer and nontumorigenic cell lines." (PMID 34494550, 2021). "As STAT3 inhibitors have not been clinically approved for cancer therapy due to their relatively low potency or nonselective toxicity or both, we used pulvomycin, a STAT3 inhibitor isolated from marine-derived actinomycetes, to treat this aggressive type of cancer." (PMID 33920736, 2021). "The mechanisms of cancer cell resistance to therapy may involve NF-kB-mediated and MAPK-mediated activities generated by TLR and NF-kB-activating inflammatory factors, along with subsequent activation of STAT3-mediated maintenance of CSC." (PMID 35048056, 2021).